ACVR1 (activin A receptor type 1)
Diseases named in the same sentence as ACVR1 in open-access papers (continued):
Sharing a sentence is not in itself a finding about the gene and the disease.
tumor (continued). "Furthermore, we characterize E6201 as a dual inhibitor of ACVR1 and MEK1/2, and demonstrate its efficacy toward tumor cells in vivo." (PMID 32142668, 2020). "To test the functional roles of ASCL1 and SOX11 in DIPG tumor cells, we used CRISPR/Cas9-mediated gene editing to inactivate them individually and in combination in ACVR1 mutant (SU-DIPG-IV, SU-DIPG-XXI, SU-DIPG-XXXVI, HSJD-DIPG-007) or wild-type (SU-DIPG-VI) cells." (PMID 32142668, 2020). "Although seven different ACVR1 mutations have been reported in DIPG, the most common alteration in this tumor type, p.Gly328Val, has not been reported in FOP patients." (PMID 26175967, 2015). "However, one H3-WT tumour without EZHIP overexpression (zcc446) was aneuploid with a high density of single nucleotide and structural variants and lacking either ACVR1 or EGFR mutations." (PMID 36882456, 2023). "Especially increased binding of TGF-β related ligand-receptors such as ACVR1- TGFBR1 ligand-receptors pairs, indicating that although the infiltration of T cells in the high-risk group increased, most of the T cells were depleted and did not exert anti-tumor functions." (PMID 39575251, 2024). "Despite being an amenable drug target, little has been done to-date to systematically evaluate the role of ACVR1 in DIPG, nor to screen currently available inhibitors in patient-derived tumour models." (PMID 31098401, 2019). "While not statistically, ACVR1 R206H, Cre, and PDGFA tumors lysates showed increased phosphorylated pSTAT3 levels as compared to RCAS Y, Cre, and PDGFA tumor lysates." (PMID 30833574, 2019).
cancer (40 papers, 2012 to 2025). A tumor composed of atypical neoplastic, often pleomorphic cells that invade other tissues. "Activin A receptor type I (ACVR1), known for encoding the type I receptor for bone morphogenetic proteins (BMPs), has been identified as a cancer diver gene across various tumors." (PMID 39924917, 2025). "We conjecture that the increased kinase activity of the ACVR1 G328V mutation interferes with essential drivers of cancer progression in vivo." (PMID 32273545, 2020). "Carcinomas with copy number gains of ACVR1 had increased expression of ACVR1 and were associated with longer survival." (PMID 31683698, 2019). "The presence of H3.1K27M in midline tumors of the pons may be accompanied by upregulated Activin-A Receptor Type 1 (ACVR1) expression, a protein with proliferative and metastatic capacity implicated in numerous cancers." (PMID 38525424, 2024). "Besides FOP, mutations in the ACVR1 gene have been described as somatic events in cancer tissues from 20–30% of patients affected with Diffuse Intrinsic Pontine Glioma (DIPG)." (PMID 33562470, 2021). "In addition, ACVR1 mutations were more frequently observed in EC compared to other cancers, in both the TCGA and MSK-IMPACT datasets." (PMID 34360647, 2021). "High stromal ACVR1 expression in areas of cancer invasion was significantly correlated with poor disease-free survival (DFS)." (PMID 40745121, 2025). "This distance was significantly reduced in the cancerous region, suggesting that BMP7-positive cancer cells and ACVR1-positive stromal cells interacted within the stromal area near the advanced cancer invasion front." (PMID 40745121, 2025). "Using ligand–receptor analysis of reproducible fibroblast clusters, we focused on the cancer cell BMP7–fibroblast ACVR1 axis." (PMID 40745121, 2025). "ACVR1 can physically cross-talk to TβRI at both the receptor and/or Smad levels in several types of human cancers despite little knowledge of their antagonism or synergy in the DIPG context." (PMID 32273545, 2020). "These compounds also increase the survival of mice carrying ACVR1 mutant brainstem xenografts, suggesting ALK2 as a potential pharmacological target against this lethal cancer." (PMID 31098401, 2019). "As detailed above, ACVR1 is a well-known cancer driver due to its essential role in diffuse intrinsic pontine glioma initiation and progression." (PMID 31683698, 2019). "We focused on one of these combinations, BMP7 in cancer cells and ACVR1 in stromal cells." (PMID 40745121, 2025). "Additionally, we investigated cancer cell–fibroblast crosstalk, focusing on the expression of activin receptor type I (ACVR1) in fibroblasts and bone morphogenetic protein 7 (BMP7) in cancer cells as potential therapeutic targets." (PMID 40745121, 2025). "It is possible that high INHBA expression levels may facilitate the formation of INHBA homodimers, otherwise known as Activin A, leading to the activation of activin receptors such as ACVR1, which has established roles in cancer." (PMID 34642171, 2022). "New research shows that ACVR1 plays an important role in human cancer." (PMID 34725559, 2021). "Alterations in PI3K, which has a central role in cancer biology, may affect ACVR1-related DIPG oncogenesis." (PMID 31683698, 2019). "All these data have strongly validated ACVR1 as a cancer driver in DIPG." (PMID 31683698, 2019). "ACVR1 has not been previously implicated in cancer, thus the link with a mutated histone H3 variant in the context of glioma is particularly intriguing." (PMID 28649369, 2017). "However, patients with FOP are at no greater risk of DMGs (or any other cancers), indicating that ACVR1 mutations alone are not sufficient for tumorigenesis." (PMID 34944870, 2021). "Therefore, ACVR1 should be considered a complex regulator of cancer biology." (PMID 31683698, 2019). "However, FOP patients with identical ACVR1 mutations do not present increased oncogenic predisposition to cancer or DIPG." (PMID 31683698, 2019).
cancer (continued). "Using single-cell analysis, we investigated cancer-fibroblast crosstalk, with emphasis on activin receptor type I (ACVR1) in fibroblasts and bone morphogenetic protein 7 (BMP7) in cancer cells as potential therapeutic targets." (PMID 40745121, 2025). "The correlation between high ACVR1 and BMP7 expression levels and the prognosis of patients with stage II cancer was evaluated." (PMID 40745121, 2025). "PDAC cancer stem cell markers including CD44, MET, CD133, FUT4, ACVR1, mTOR, and KLF4 were positively related to IARS2 expression." (PMID 40092487, 2025). "Other known recurrent cancer genes with ≥10 occurrences include PLEC, PDGFRA, NF1, ARID1A, BCOR, and ACVR1." (PMID 41312385, 2025). "This included genes like, PIK3R2, PIK3CA, BIRC2 and ZBTB14 with implications in cancer that were over-expressed with FC above ≥10 in OS-DW in comparison to OS-R; while, expression of WNT5A, PIK3CB, ACVR1, MAPK13 and GBX2 were significantly reduced." (PMID 31690262, 2019). "It was shown that MAP3K14, PTN, ACVR1 and HCK sharing different DNA methylation and gene expression across cancers were relatively high degree distribution in PPI network." (PMID 25774687, 2015). "Although not listed by IntOGen for these cohorts, ACVR1 and CXCR4 have been implicated in the tumorigenesis of both cancers." (PMID 40768543, 2025). "Such a scenario suggests that in cancer and EMT, TGF-β signaling could undergo modulation in trans by TGFBR1/ACVR1 signaling." (PMID 38753874, 2024). "KEGG analysis showed that ACVR1, SMAD1, ZFYVE9, BMPR1B, and TGFB3 were related to regulating proteoglycan in cancer, focal adhesion, tight junction, PI3K-Akt signaling pathway, cell adhesion molecules (CAMs), Rap1 signaling pathway, osteoclast differentiation, and Hippo signaling pathway." (PMID 34725559, 2021). "Interestingly, ACVR1 mutations appear to be unique to DMG tumors and are not present in other cancers; however, they are closely associated with the genetic condition fibrodysplasia ossificans progressive (FOP)." (PMID 34944870, 2021).
genetic disorder (28 papers, 2009 to 2025). "Fibrodysplasia ossificans progressive (FOP) is an ultra-rare genetic disorder that is caused by a mutation in the ACVR1 gene and provokes severe heterotopic ossification." (PMID 37644581, 2023). "Fifteen years ago, a gain-of-function mutation in the ALK2/ACVR1 gene was detected in patients with the genetic disorder fibro-dysplasia ossificans progressiva, which is characterized by heterotopic ossification in soft tissues." (PMID 34206903, 2021). "There has been long-standing interest in developing drugs for this genetic disorder, even preceding the discovery of ACVR1 as the causative gene." (PMID 28629737, 2018). "Of note, one of the patients was also positive for the p.R206H mutation in ACVR1, raising the question of the likelihood that two “pathogenic” mutations causing a genetic disorder as rare as FOP would be found in a single patient." (PMID 22529972, 2012). "Another example of iPSC application regards fibrodysplasia ossificans progressiva (FOP), a genetic disease caused by a heterozygous missense mutation in the activin receptor-like kinase 2 gene (ACVR1/ALK2) and characterized by progressive heterotopic ossification of soft tissues." (PMID 32121221, 2020). "Fibrodysplasia ossificans progressive (FOP), a rare genetic disorder that caused by a gain‐of‐function mutation in the GS regulatory domain of the bone morphogenetic protein (BMP) type I receptor, ACVR1 (ALK2), is also formed via endochondral ossification." (PMID 32293797, 2020). "Hyperactive mutations in the bone morphogenetic protein (BMP) type 1 receptor ACVR1 lead to fibrodysplasia ossificans progressiva (FOP), a rare genetic disorder characterized by progressive ossification in soft tissues." (PMID 24321451, 2013).
infection (8 papers, 2013 to 2025). The state of being infected such as from the introduction of a foreign agent such as serum, vaccine, antigenic substance or organism. "Infection with all ACVR1 mutations led to increased phosphorylated SMAD1/5/8 expression as compared to ACVR1 WT, with ACVR1 G328E increasing pSMAD1/5/8 modestly but significantly relative to ACVR1 WT." (PMID 30833574, 2019). "Id1 levels were also significantly up-regulated by infection with ACVR1 mutations relative to ACVR1 WT with ACVR1 G328V increasing Id1 protein levels the most." (PMID 30833574, 2019). "However, infection with ACVR1 mutations and H3.1K27M did not significantly increase phosphorylated STAT3 Y705 expression compared to infection with ACVR1 mutations alone." (PMID 30833574, 2019). "(B) Gene expression analysis of Pik3caα in BM-MSCs from Pik3cafl/fl mice, infected with virus expressing wild-type Acvr1 (WT) or Acvr1R206H (RH) and/or Cre co-infection." (PMID 40525393, 2025). "Infection with ACVR1 R206H virus significantly increased proliferation relative to ACVR1 G328V and ACVR1 G328E and cell survival relative to ACVR1 WT and ACVR1 G328E." (PMID 30833574, 2019). "Furthermore, silencing ACVR1 with siRNA resulted in a reduction in the comet tail length following infection with H. pylori." (PMID 39924917, 2025). "The upregulation of ACVR1 and the suppression of POLD1 upon H. pylori infection establish a connection between the infection, genomic instability, and the development of gastric carcinogenesis." (PMID 39924917, 2025).
autosomal dominant disease (3 papers, 2020 to 2022). Autosomal dominant form of disease. "This mutation has been previously reported only as a germline mutation in a congenital autosomal dominant disease of the connective tissue called fibrodysplasia ossificans progressive (FOP), but the typical ACVR1 alteration found in DIPG (p.Gly328Val) has not been reported in FOP patients." (PMID 36140466, 2022).
brain diseases (1 paper, 2022). "Out of these three receptors, we first focused on ACVR1, a Type I receptor that is expressed in a variety of cell types and plays key roles in bone and brain diseases, and asked whether reducing its expression could make ligand responses in NMuMG cells more similar to those of mESCs." (PMID 35421361, 2022).
CNS tumor (1 paper, 2014). "The lack of reported CNS tumor development in FOP patients or Acvr1/Alk2 mouse models suggests that aberrant activation of this pathway is not sufficient for tumorigenesis." (PMID 25077668, 2014).
endocrine disorders (1 paper, 2023). "The identification of common pathogenic mechanisms in monogenic and endocrine disorders associated with OPLL/DISH, and the development of targeting therapeutics for other relevant pathways such as ACVR1, COL11A2, COL6A, BMP2,4,9, and TGF-β1 are remaining important questions to be addressed." (PMID 37530996, 2023).
skeletal diseases (1 paper, 2013). "Our studies demonstrate the creation of iPS cells from patients with FOP, identify that ACVR1 may have a new role in regulating mineralization activity, and provide a proof-of-concept for further development of human iPS cells as disease models for studying human skeletal diseases." (PMID 24321451, 2013).
ACVR1 also shares sentences with these, for which no sentence is quoted: multiple myeloma (6 papers); chondrosarcoma (2); connective tissue disease (2); diffuse idiopathic skeletal hyperostosis (2); hemochromatosis (2); iron deficiency (2); metabolic disease (2); musculoskeletal disease (2); nephrolithiasis (2); osteosarcoma (2); pancreatic ductal adenocarcinoma (2); skeletal dysplasia (2); acute kidney injury (1); acute myeloid leukemia (1); alopecia (1); ankylosing spondylitis (1); Anxiety (1); aortic stenosis (1); aortic valve disorder (1); atherosclerosis (1); atrial septal defect (1); autoimmune thyroid disease (1); benign prostate tumors (1); bladder cancer (1); brain malformation (1); brainstem tumour (1); cardiac disease (1); chronic lymphocytic leukaemia (1); cleft lip (1); cognitive decline (1).
A further 46 diseases each share a sentence with ACVR1 in 1 paper.